IL6 (interleukin 6)
Diseases named in the same sentence as IL6 in open-access papers (continued):
Sharing a sentence is not in itself a finding about the gene and the disease.
myeloma (continued). "On the one hand, myeloma cells hijack stromal cells to secrete cytokines, such as interleukin-6 (IL-6), receptor activator of NF-κB ligand (RANKL) and vascular endothelial growth factor (VEGF), to promote cancer proliferation and angiogenesis." (PMID 32781681, 2020). "In the serum of multiple myeloma patients with inflammation (patients with plasma C-reactive protein > 10 mg/dL), hepcidin is abnormally increased, together with interleukin-6 (IL-6)." (PMID 33255972, 2020). "Taken together, these results suggest that augmented IL-6 production by peripheral T lymphocytes influences the immune dysfunction described in MM and allows myeloma cells to escape immune surveillance by inhibiting the antitumor Th1 immune response." (PMID 31185596, 2019). "More recently, it has been demonstrated to promote the growth of myeloma cells in IL-6-deprived cultures." (PMID 31185596, 2019). "Endothelial cells that receive CD138 from multiple myeloma derived MVs are significantly stimulated so as to proliferate, secrete IL-6 and VEGF, two key angiogenic factors of myeloma, and form tubes in vitro and in vivo." (PMID 30925930, 2019). "PACAP1-38 suppressed myeloma-stimulated interleukin 6 (IL-6) secretion by the bone marrow stromal cells." (PMID 31540472, 2019). "In myeloma there are high levels of inflammatory cytokines such as interleukin-6 and tumor necrosis factors." (PMID 31741612, 2019). "PI3K/Akt or MAPK/ERK signal activation triggered by IL-6 has been reported to induce cancer cell proliferation through the upregulation of cyclin A1 in hepatoma, prostate cancer, and multiple myeloma." (PMID 30927911, 2019). "The interaction between IL-6 and IL-6R was shown to induce antiapoptotic effects on human esophageal carcinoma and multiple myeloma through the phosphorylation of gp130 and STAT3." (PMID 31252615, 2019). "Interleukin 6 (IL-6) is an important growth factor in MM cells, and IL-6-related signaling pathway has been shown to regulate MM cell proliferation and programmed cell death in myeloma." (PMID 31915680, 2019). "IL-1 promotes the growth of myeloma cell lines and indirectly operates on myeloma plasma cells through IL-6 generation via a prostaglandin E2 (PGE2) loop." (PMID 31185596, 2019). "IL6 is regarded as a possible target in multiple myeloma; monocytes constitute a subset of the bone marrow stromal cells that are regarded as important regulators of both normal and malignant hematopoietic cells." (PMID 31703617, 2019). "In monoclonal gammopathies, IL-6 has been recognized as a crucial growth factor for human myeloma cells." (PMID 31185596, 2019). "IL-6 promotes myeloma cell proliferation both in vitro and in vivo, and the IL-6 level is correlated with myeloma progression." (PMID 31334678, 2019). "High expression of Notch1, 2, and Jagged1 can be correlated with tumor progression of myeloma and it was proposed that Notch has an activating role of interleukin 6 (IL-6) proliferating signals in the bone marrow, enhancing tumor growth." (PMID 30917608, 2019). "Inhibition of growth in myeloma cells through IL-6 suppression is mediated through the human PAC1 receptor short subtype and/or VPAC2 receptor." (PMID 31591326, 2019). "Contrary to the stem cell niche, IL-6 is the major contributor for myeloma cells in the bone marrow." (PMID 31737046, 2019). "In vivo and in vitro studies of multiple myeloma demonstrated that bone-marrow derived exosomes contain high levels of interleukine-6 (IL-6) and this interaction of exosomal IL-6 with multiple myeloma cells inhibited tumor cell apoptosis." (PMID 30925921, 2019). "In many types of cancers including multiple myeloma, autocrine secretion of IL-6 is known to inhibit DCs migration function." (PMID 31164886, 2019). "Remarkably, a previous study revealed that RMP mediated the chemoresistance of multiple myeloma through NF-κB/IL-6/STAT3 signaling pathway." (PMID 31754340, 2019).
myeloma (continued). "IL-6 is a growth factor for myeloma cells that also promotes their survival and is produced in the BM microenvironment." (PMID 30376895, 2018). "Upon adhering to myeloma cells, BMSCs activate the canonical NF-κB pathway, which induces the expression of IL-6." (PMID 29772694, 2018). "Production of IL-6 by stromal cells is of relevance in MM, as evidenced by the induction of PD-L1 by IL-6 on human myeloma cell lines, which can be downregulated by inhibiting STAT3, MEK1/2, or JAK2." (PMID 29580288, 2018). "They reported that the most significantly upregulated gene was IL6, and the most significantly associated pathway for genes-set was MAPK signaling in WM compared to chronic lymphocytic leukemia (CLL) and multiple myeloma (MM)." (PMID 30402490, 2018). "The allosteric AKT inhibitor MK2206 was also found in myeloma cells to overcome bortezomib resistance induced by IL-6 or MSCs." (PMID 29765356, 2018). "NF-κB up-regulates both intracellular adhesion molecules and vascular cell adhesion, and inhibits IL-6 secretion resulting from adhesion of multiple myeloma cells to bone marrow stroma." (PMID 29535630, 2018). "It has been previously found that a reduction in the expression of various negative regulators of IL6/JAK/STAT pathway by epigenetic silencing can also sensitize myeloma cells to IL-6-regulated proliferation and survival." (PMID 29899697, 2018). "Osteoblasts secrete IL-6, which is a potent myeloma growth factor and promoter of osteoclastogenesis." (PMID 29098361, 2018). "In the BM of multiple myeloma patients, IL-6 is produced by tumor cells, BMSCs, and cells of the myeloid lineage, such as eosinophils, macrophages, DCs, and mast cells." (PMID 30154786, 2018). "In turn, IL-6 binds to the cognate receptor and induces pro-proliferative and pro-survival gene-expressions in myeloma cells." (PMID 29772694, 2018). "Myeloma cells that produced IL-6 in an autocrine manner were found to be resistant to dexamethasone induced apoptosis while non-IL-6 producing cells were sensitive." (PMID 30061485, 2018). "IL-6 is also important for the growth and survival of myeloma cells, and it can stimulate osteoclastogenesis." (PMID 30211233, 2018). "Engagement of CD40 enhances adhesion of myeloma cells to extracellular matrix proteins and BMSCs, and induces the production of IL-6 and VEGF by malignant cells." (PMID 29772694, 2018). "The pro-tumor macrophages enhance myeloma cell proliferation and survival by secreting IL-6 and IL-10." (PMID 30405034, 2018). "For example, transcription factor, NF-κB induced adhesion of myeloma cells to the bone marrow stromal cells promotes the secretion of IL-6 by the stromal cells." (PMID 29773987, 2018). "Using an immortalized bone marrow stromal cell line or conditioned media from these cells, the authors induced resistance to either venetoclax or ABT-737 in myeloma cell lines, and this resistance was reversed by a neutralizing IL-6 antibody." (PMID 30406027, 2018). "Multiple myeloma (MM) is a blood cancer that homes to the BMM and is strongly tied to overexpression of IL-6 and bone loss." (PMID 30671025, 2018). "In myeloma progression, IL-6 promotes tumor cells growth, osteoclastogenesis, resistance to therapy, and, importantly, contributes to the development of an immunosuppressive milieu in the BM niche." (PMID 30154786, 2018). "IL-1β is an osteoblast activating factor which plays an important role in the bone lesion by multiple myeloma cells, and promotes the proliferation of myeloma cells by inducing IL-6 generation." (PMID 30211233, 2018). "Bortezomib has been reported to affect myeloma cell growth by the blockade of NF-κB and down-regulation of cytokines, such as IL-6." (PMID 30376895, 2018). "The results of previous studies suggest that in myeloma CRP concentration is dependent on IL-6 activity and indirectly reflects the state of bone marrow microenvironment." (PMID 29844872, 2018).
myeloma (continued). "In the development of MM, the NF-κB and PI3K-AKT-mTOR signaling pathways are activated, which induce bone marrow stromal cells to secrete abundant IL-6 and growth factors, contributing to the growth, proliferation and survival of myeloma cells." (PMID 30186161, 2018). "In other malignancies, such as multiple myeloma and gastric cancer, Notch ability to drive IL-6 secretion has been observed also in the surrounding stromal cells of the TME." (PMID 30154786, 2018). "TNF-α is one of the major pro-inflammatory cytokines secreted from myeloma cells and can stimulate bone marrow stromal cells to release IL-6, which can act as a potential growth factor for myeloma cells." (PMID 29773987, 2018). "In another study, it was found that a significant increase in IL-6 concentration occurred when the myeloma cells were cocultured with BM MSCs of MM patients in a non-contact Transwell system." (PMID 29535427, 2018). "It was suggested that bFGF, secreted by myeloma cells, bound to bFGF receptors on BM MSCs and thus stimulated IL-6 production." (PMID 29535427, 2018). "Taken together, we discovered and described five lncRNAs, termed STAiRs, which are induced by IL-6-activated STAT3 in INA-6 multiple myeloma cells." (PMID 28801664, 2017). "APRIL can promote the survival of malignant plasma cells and rescue myeloma cell lines from apoptosis after IL-6 deprivation." (PMID 31548533, 2017). "Interleukin-6 (IL-6): Increased concentrations of IL-6 have been identified in hypercalcemic patients with multiple myeloma, squamous cell carcinoma and ATLL." (PMID 29056680, 2017). "This increased IL-6 production is sufficient to drive resistance of malignant plasma cells to bortezomib, a highly clinically relevant anti-myeloma drug." (PMID 27400413, 2017). "IL-6 has been identified as a major growth factor for the differentiation of B cells to antibody-producing plasma cells and in myeloma cell growth." (PMID 28467797, 2017). "TQ also found to impede constitutive and IL-6-inducible STAT3 phosphorylation in U266 multiple myeloma cells, as well as inhibit c-Src and JAK-2 activation." (PMID 28983249, 2017). "We found that GAC 17:1 inhibited both constitutive and IL-6-inducible STAT3 activation in multiple myeloma cells along with the abrogation of c-Src and JAK2 activation and the induction of PTEN and SHP-1 proteins." (PMID 28208828, 2017). "IL-6 was also found to act on neuroblastoma and multiple myeloma cells within the bone marrow by increasing cell proliferation and survival through activation of the signal transducer and activator of transcription 3 (STAT3) pathway." (PMID 28148268, 2017). "Dysregulation of IL-6 signaling contributes to the onset and maintenance of several diseases including some types of cancer, i.e. multiple myeloma, gastric cancer and prostate cancer." (PMID 28903416, 2017). "Production of IL-6 in multiple myeloma by bone marrow stromal cells induces tumour cell adhesion and osteoclastogenesis." (PMID 28148268, 2017). "In the microenvironment of multiple myeloma patients, dendritic cells and IL-6, IL-23 and IL-1 are involved in increased Th17 cells, which increase IL-17 and can promote osteoclast and myeloma proliferation." (PMID 28800754, 2017). "IL-6 has been identified as a major growth factor for myeloma cell proliferation in vivo and in vitro." (PMID 28467797, 2017). "In the BM environment, stromal cells react to low levels IL-1 and produce large quantities of IL-6, which in turn stimulate the survival of the myeloma cells." (PMID 29089667, 2017). "Enhancing sensitivity of the myeloma cell to IL-6 contributes to the growth and expansion of the neoplastic cells, as is the case with the soluble receptors for IL-6 (sIL-6R)." (PMID 28099912, 2017). "Interleukin-6 increased the proliferation of multiple myeloma cells and TNIK mRNA and protein expression." (PMID 28467797, 2017).
myeloma (continued). "The IL6/STAT3 activation enhances myeloma cell survival through the activation of anti-apoptotic genes, Mcl-1, Bcl-XL and c-Myc oncogene." (PMID 28458781, 2017). "Direct evidence has shown that IL1-β plays an important role in multiple myeloma, and when released, this cytokine induces IL-6 production by bone marrow stromal cells and acts as an autocrine growth factor for myeloma cells." (PMID 28785138, 2017). "IL-6, a growth factor for multiple myeloma cells, is overexpressed in various cancers and is a potent inducer of STAT3." (PMID 28208828, 2017). "Originally identified as a regulator of normal B-cell differentiation, IL-6 has shown to promote myeloma cell proliferation and protect cells from apoptosis." (PMID 28099912, 2017). "In this study, we introduce STAiRs, five IL-6/STAT3-induced long ncRNAs in INA-6 multiple myeloma cells." (PMID 28801664, 2017). "Following treatment with BI836909, selective lysis of BCMA-positive myeloma cells, activation and proliferation of T cells, as well as release of multiple key cytokines related to effector T cell function (IFNγ, IL-2, IL-6, TNFα, IL-10) were noted." (PMID 31548533, 2017). "Myeloma cells rely on the pleiotropic cytokine interleukin-6 (IL-6), which is hallmarked by a wide range of biological functions, including immune regulation, hematopoiesis, inflammation, and tumor development." (PMID 28801664, 2017). "Here, we investigated the relationship between interleukin-6-induced proliferation of multiple myeloma cells and Traf2- and Nck-interacting kinase (TNIK) expression in Wnt signaling." (PMID 28467797, 2017). "We demonstrated for the first time that GAC 17:1 can inhibit activation of STAT3 in U266 cells and also found that GAC 17:1 suppressed IL-6-induced STAT3 activation in multiple myeloma and MEF cells." (PMID 28208828, 2017). "Nevertheless, IL-6 not only participates in the proliferation of myeloma cells, but also is a main morbidity factor in MM subjects." (PMID 29089667, 2017). "Interleukin-6 (IL-6) secreted from transformed MSCs in turn favors the survival of multiple myeloma (MM) cells." (PMID 29333170, 2017). "To determine if inflammatory cytokine signaling contributes to ADAR1 activation in MM, as reported in other contexts, we treated the 1q-amplified human myeloma cell line H929 with increasing concentrations of IL-6 (0–10 ng/ml) in vitro." (PMID 29203771, 2017). "Among the most studied of these cytokines is IL-6, which is chiefly produced by bone marrow stem cells and macrophages and is an important mediator of myeloma cell growth, survival, migration, and drug resistance." (PMID 27363832, 2016). "In B cell malignancies, IL-6 promoted the growth and inhibited the apoptosis of multiple myeloma cells." (PMID 27128729, 2016). "IL-6 is expressed by BM stem cells and binds to the IL-6 receptor (IL-6R) on myeloma cells thereby stimulating their proliferation and survival." (PMID 27618026, 2016). "In the IL-6-dependent human myeloma cell line U266, IL-6 signals through Janus kinases to the activate STAT3, which in turn up-regulates anti-apoptotic factors, and promotes the survival of tumor cells." (PMID 26972355, 2016). "Similar phenomena was reported that hepcidin is up-regulated in multiple myeloma patients by both IL-6-dependent and -independent mechanisms." (PMID 27068103, 2016). "IL-6 is involved in proliferation, survival, and differentiation of almost all tumors studied, and is overexpressed in multiple myeloma, oral squamous carcinoma, and in breast, ovarian, prostate, endometrial, colorectal, renal, and lung cancers." (PMID 27500125, 2016). "IL-6 is essential to the survival and propagation of both normal and pathologic plasma cells and has been shown to be a required factor for myeloma clones." (PMID 27363832, 2016). "This cytokine has been shown to induce myeloma cell survival and growth and to confer sensitivity to various other gp130-activating cytokines, including IL-6." (PMID 27732933, 2016).
myeloma (continued). "A wonderful clinical example is the application of Sultuximab, an anti-IL-6 in the treatment of smoldering multiple myeloma." (PMID 27270649, 2016). "Myeloma cell lines have been found to have increase expression of the IL-6 receptor, and inhibition of IL-6 has been found to impede myeloma growth." (PMID 27363832, 2016). "On the other hand, in multiple myeloma, IL-6 production is down regulated by CREB binding to the CREB site within the IL-6 promoter region, independently of the NFκB." (PMID 27936218, 2016). "IL-6 stimulates the development of many tumours, including glioma, multiple myeloma and colorectal carcinoma." (PMID 27538520, 2016). "This antibody has been shown to inhibit IL‐6‐induced proliferation of 7TD1 myeloma cells in a dose‐dependent manner." (PMID 26739431, 2016). "Additional IL-6 targeted therapeutics are under-going clinical trials for the treatment of renal cell cancer, prostate cancer, lymphoma and multiple myeloma." (PMID 27602757, 2016). "The role of TNF-α and IL-6 in the progression of myeloma cell growth, survival, angiogenesis, and osteoclastogenesis and the inhibition of osteoblast activity is well established, as well as their adverse prognostic significance in this hematological neoplasm." (PMID 26925413, 2016). "Interleukin-6 (IL-6) is a cytokine that has long been under spotlight in myeloma since late 80s as a driver for myeloma which raised the question of benefit of targeting this cytokine for theurapeutic purposes." (PMID 26784207, 2016). "It is well known that NF-κB plays an important role in promoting growth, survival, and chemoresistance of myeloma cells in BM through the regulation of IL-6 and insulin-like growth factor 1 (IGF-1) expression." (PMID 26579531, 2015). "Our findings establish a relationship between CD45 isoforms’ microdomain locations and the regulation of IL-6-mediated myeloma cell activation." (PMID 25781885, 2015). "In MM, IL-6 is auto-secreted by myeloma cells and para-secreted mainly by bone marrow stromal cells." (PMID 25865044, 2015). "IL-6 binds to the sIL-6R receptor (IL-6R) on the myeloma cell surface and induces dimerization of gp130 chains, then results in activation of the associated Janus kinase (JAKs)." (PMID 25865044, 2015). "The growth stimulatory effect of IGF1 and IL-6 on multiple myeloma cells was completely abrogated by NPV-BGT226." (PMID 26405162, 2015). "Other inflammatory cytokines known to support myeloma growth, such IL6 and CCL3 were also secreted into the supernatant after stimulation of the bone marrow monocytes with the TLR8 agonist." (PMID 26029369, 2015). "Myeloma-secreted TNFs can also induce BMSCs to secrete IL-6 (the main secreted myeloma cell growth and survival factor) locally and modulate cell-cell adhesion between myeloma cells and BMSCs in the bone microenvironment." (PMID 26009993, 2015). "Our findings also elucidate a previously unrecognized mechanism by which CD45 isoforms differentially regulate IL-6 signaling in myeloma cells." (PMID 25781885, 2015). "The data presented here extends the finding from our previous research that demonstrates the important regulative role of CD45 isoforms in IL-6-induced myeloma cells proliferation." (PMID 25781885, 2015). "IL-6 plays an essential role in the final differentiation of B cells into IG-secreting cells, as well as inducing myeloma/plasmacytoma growth, nerve cell differentiation, and, in hepatocytes, acute-phase reactants." (PMID 26798399, 2015). "Within the growth signalling network of the myeloma microenvironment, IL-6, IGF-1 and insulin play a prominent role." (PMID 25887188, 2015). "Multiple myelomas are characterized by excessive production of plasma cells in the bone-marrow and require IL6 signaling to promote cell growth and survival through activation of the ERK and PI3K signaling cascade." (PMID 26087188, 2015).